FOXP3 (forkhead box P3)
Diseases named in the same sentence as FOXP3 in open-access papers (continued):
Sharing a sentence is not in itself a finding about the gene and the disease.
Infertility (13 papers, 2012 to 2025). "In cattle, the FOXP3 gene plays an important role in regulating immune responses and immune system development and is believed to be associated with infertility in bovine species." (PMID 40867735, 2025). "Recently, an X-linked maternal single-nucleotide polymorphism (SNP) in the upstream of the bovine FOXP3 gene (NC_037357.1: g.87298881A>G, rs135720414) was identified in Japanese Black (JB) cows in association with recurrent infertility." (PMID 35454290, 2022). "This SNP was associated with a reduction in FOXP3 transcription, which in turn was linked to a reduction in the number of maternal Treg cells and led to infertility or repeat breeding." (PMID 35454290, 2022). "In line with this, it was recently reported that diminished endometrial Foxp3 mRNA was associated with infertility in women." (PMID 23801995, 2013). "Accordingly, this variant may be a useful target for initiatives to increase cattle herd fertility because of the relationship between a higher frequency of the G allele variant of the FOXP3 gene and recurrent infertility in JB cows." (PMID 40867735, 2025). "A previous GWAS identified a FOXP3 gene variant (NC_037357.1: g.87298881A>G, rs135720414) associated with repeat breeding in JB cattle, indicating that the G allele is a variant associated with infertility." (PMID 40867735, 2025). "In conclusion, the G allele of the FOXP3 gene variant may potentially be associated with infertility in different bovine breeds and species." (PMID 40867735, 2025). "We hypothesized that the frequency of the FOXP3 gene variant may be associated with infertility in these cattle breeds and species because one of the Asian local cattle, IM, has a high frequency (0.700) of the G allele variant." (PMID 40867735, 2025). "Our results suggest that the G allele of the FOXP3 gene variant may be originally a wild-type variant in cattle breeds and water buffalo and that the G allele may be associated with infertility in cattle and other bovid species." (PMID 40867735, 2025). "Recently, an X-linked maternal single-nucleotide polymorphism (SNP), located 2175 base pairs upstream of the start codon in the bovine FOXP3 gene (NC_037357.1: g.87298881A>G, rs135720414), was identified in Japanese Black (JB: Bos taurus) cows in association with recurrent infertility." (PMID 35454290, 2022). "Therefore, this study aimed to study the difference of FoxP3+ expression in endometrial tissue during the peri-implantation window between patients with EM-associated infertility and healthy fertile women." (PMID 22541024, 2012). "However, very little is known about the role of FoxP3+ Tregs in the pathophysiologic mechanism of EM-associated infertility and the changes of FoxP3+ Treg population in different EM stages." (PMID 22541024, 2012). "Therefore, infertility in bovine herds may be improved by the selection and/or introduction of the A allele of the bovine FOXP3 gene." (PMID 40867735, 2025). "Reporter assays indicated that this SNP G allele was associated with reduced levels of FOXP3 transcription, which may be a maternal immunogenic factor underlying the identified association between recurrent infertility in repeat breeding cows and higher frequencies of the G allele." (PMID 35454290, 2022). "↑↑ Decidua.↑ T reg count and percentage during pregnancy.↓ Cell count in unexplained infertility and miscarriage.↓ FOXP3 expression." (PMID 39885993, 2024). "In primarily unexplained infertility, a reduced endometrial expression of FoxP3 has been reported, as well as successful IVF cycles seem associated with an increase of Tregs in the peripheral blood." (PMID 31906232, 2019). "This study aimed to investigate the pathogenesis of infertility in women with EM by comparing FoxP3+ T regulatory cells (Tregs) expression in the eutopic endometrium of infertile women with EM and endometrium from healthy fertile women." (PMID 22541024, 2012).
Infertility (continued). "Further analysis based on the extent of EM revealed that FoxP3 mRNA expression in infertile patients with advanced EM was significantly higher than the mild EM group and the control group (P < 0.05)." (PMID 22541024, 2012). "Analysis of FoxP3 mRNA expression by quantitative real-time RT-PCR revealed that infertile women with EM have higher levels of FoxP3 mRNA in eutopic endometrium than the control group." (PMID 22541024, 2012). "In this study, FoxP3 expression in the endometrium during the peri-implantation phase was investigated by comparing infertile women with different stages of EM to normal fertile women." (PMID 22541024, 2012). "Therefore, it is hypothesized that FoxP3+ Tregs in the peri-implantation endometrium participate in the pathogenesis of EM while they are not directly involved in the pathogenesis of advanced EM associated infertility." (PMID 22541024, 2012). "Further analysis based on the extent of EM revealed that infertile women with advanced EM have higher levels of FoxP3 mRNA in eutopic endometrium than women with mild EM and the control group." (PMID 22541024, 2012). "As a marker of Tregs, FoxP3 expression was analyzed in eutopic endometrium during the peri-implantation phase in infertile women with mild EM (n = 7), advanced EM (n = 20), and normally fertile women without EM (n = 20)." (PMID 22541024, 2012). "FoxP3 mRNA expression in all infertile patients with EM was significantly higher than the control group (P < 0.05) by non-parametric Mann–Whitney U-test." (PMID 22541024, 2012). "FoxP3 expression in the endometrium of infertile patients with EM compared to healthy fertile women remains to be elucidated." (PMID 22541024, 2012). "This GWAS identified a maternal variant in the upstream region of FOXP3 that was associated with infertility in repeat-breeding Japanese Black cattle that failed to conceive using ET." (PMID 29212449, 2017). "Interestingly, human infertile women have very low levels of endometrial Foxp3, supporting the relevance of Tregs for implantation." (PMID 26136750, 2015). "Similarly, infertile patients have critically diminished Foxp3 mRNA levels in endometrium, supporting the concept of Foxp3+ Treg importance for pregnancy establishment." (PMID 26136750, 2015). "Furthermore, FoxP3 expression in the endometrium of infertile patients with different stages of EM and the role of Tregs in the etiology of infertility in women with EM were investigated as well." (PMID 22541024, 2012). "Additionally, our study showed that the expression of FoxP3 mRNA in the infertile women with mild EM was significant lower than patients with advanced EM, but it was similar to the control group." (PMID 22541024, 2012). "Further analysis based on the extent of EM revealed that FoxP3 mRNA expression in infertile patients with advanced EM (median, 1.20; interquartile range, 0.86-1.95) was significantly higher than the mild EM group (median, 0.38; interquartile range, 0.21-0.47) and the control group (P < 0.05)." (PMID 22541024, 2012). "The differential expression of FoxP3 in infertile women with mild EM and advanced EM implicates that notable differences in the uterine immune status are likely involved in the pathogenesis of mild EM associated with infertility in the peri-implantation endometrium." (PMID 22541024, 2012). "However, the actual function of FOXP3 and the influence of FOXP3 PV in human infertility remain unknown." (PMID 31855573, 2019). "The current GWAS detected six QTLs on the X chromosome and identified a maternal variant in the upstream region of the FOXP3 gene, which is located in QTL_2, which was associated with infertility in repeat-breeding Japanese Black heifers that failed to conceive following ET." (PMID 29212449, 2017).
Infertility (continued). "In addition, the number of FoxP3+ cells in the eutopic endometrium of infertile women with advanced EM was marginally higher than the mild EM group and the control group, although the differences were not statistically significant (P > 0.05) by two-tailed t-tests." (PMID 22541024, 2012). "This study explored the relationship between an X-linked single-nucleotide variant (NC_037357.1: g.87298881A>G, rs135720414) in the upstream of the bovine forkhead box P3 (FOXP3) gene and infertility." (PMID 40867735, 2025). "Therefore, the crucial role of FoxP3+ Tregs in endometrial receptivity and embryo implantation dictates the need for alternative therapeutic approaches to support endometrial FoxP3 activation and the periconceptional expansion of the CD4+CD25+ Tregs in infertile women, especially those with PCOS." (PMID 33808965, 2021). "It is not clear whether the inadequate numbers of FoxP3+ Tregs in the peri-implantation endometrium in sub-fertile women with mild EM is related to the pathogenesis of infertility and unsuccessful embryo implantation." (PMID 22541024, 2012).
lung fibrosis (13 papers, 2010 to 2025). "In patients with idiopathic pulmonary fibrosis (IPF), the expression of SEMA7A on CD4+CD25+FoxP3+ regulatory T cells (Tregs) is associated with disease progression." (PMID 40182927, 2025). "Counterintuitive findings from another study showed that exogenous administration of the AHR ligand FICZ ameliorated pulmonary fibrosis, presumably by augmenting numbers of FoxP3+ Tregs and decreasing IFN-γ+ CD4+ and IL-17A+ γδ+ T cells." (PMID 39964756, 2025). "Given the established role of Tregs in the resolution of lung fibrosis, we evaluated the effects of hAECs in bleomycin-injured FoxP3-GFP mice, where FoxP3+ Tregs express GFP." (PMID 25634246, 2015). "Recent results also indicated that regulatory T cells CD4+ Foxp3+ (T regs) accumulated during the development of pulmonary fibrosis, possess a strong fibrotic activity in mice treated with silica." (PMID 25050810, 2014). "Depletion of CD4+CD25+Foxp3+ Treg cells enhanced Th1 response and decelerated Th1/Th2 balance toward a Th2 phenotype in silica-induced lung fibrosis." (PMID 21072213, 2010). "Secondly, we want to investigate the regulatory role of CD4+CD25+Foxp3+ Treg cells in silica-induced lung fibrosis by studying the mRNA expression of typical Th1 (IL-2, IFN-γ) and Th2 (IL-4) cytokines." (PMID 21072213, 2010). "We next sought about the mechanisms of CD4+CD25+Foxp3+ regulatory T cells in silica-induced lung fibrosis." (PMID 21072213, 2010). "Depletion of CD4+CD25+Foxp3+ regulatory T cells limited and delayed the Th2 responses in silica-induced lung fibrosis." (PMID 21072213, 2010). "These suggested that CD4+CD25+Foxp3+ regulatory T cells played a regulatory role in silica-induced lung fibrosis by modulating Th1/Th2 balance." (PMID 21072213, 2010). "Depletion of CD4+CD25+Foxp3+ regulatory T cells enhanced Th1 response at the later stage of lung fibrosis." (PMID 21072213, 2010). "The regulatory function of CD4+CD25+Foxp3+ Treg cells in silica-induced lung fibrosis depends on direct mechanism at the inflammatory stage and indirect mechanism during the fibrotic stage in silica-induced lung fibrosis." (PMID 21072213, 2010). "And in our study, depletion of CD4+CD25+Foxp3+ regulatory T cells indeed limited and delayed the Th2 responses in silica-induced lung fibrosis." (PMID 21072213, 2010). "Therefore, to investigate the role of Tff1 in Tregs during pulmonary fibrosis, we generated Foxp3-Cre/Tff1fl/fl mice, in which Tff1 expression in Tregs was specifically disrupted." (PMID 39286257, 2024). "Overexpression of TGF-β may increase lung fibrosis through sustained or unbalanced proportions of Foxp3+ T cells in the lung." (PMID 34941793, 2021). "In this study, we observed the effects of CpG on radiation-induced pulmonary fibrosis, detected the effects of CpG on the serum TGF-β1 and preliminary explored if this effect was related to the CpG FoxP3 gene." (PMID 27190497, 2016). "To determine the mechanism of Treg cells in silica-induced lung fibrosis, we first examined the effective fraction (CD4+CD25+Foxp3+ Treg cells) in HLN, spleen and BALF." (PMID 21072213, 2010). "To investigate the role of CD4+CD25+Foxp3+ regulatory T cells in silica-induced lung fibrosis, we first assessed the population of CD4+CD25+Foxp3+ T cells in HLN, spleen and BALF." (PMID 21072213, 2010). "CpG ODN1826 could reduce the serum concentrations of TGF-β1 and the lung content of Hyp in radiation-induced pulmonary fibrosis, which might be related to the possibility that CpG ODN1826 can reduce expression of the FoxP3 gene." (PMID 27190497, 2016). "However, unlike in AAA, our examination using Foxp3-Cre/Tff1fl/fl mice in the BLM-induced pulmonary fibrosis model revealed that the absence of Tff1 produced by Tregs did not affect the degree of fibrosis." (PMID 39286257, 2024).
myocardial infarction (13 papers, 2013 to 2026). Gross necrosis of the myocardium, as a result of interruption of the blood supply to the area, as in coronary thrombosis. "Previous studies have shown that pyridostigmine administration, acutely after a myocardial infarction, enhances recruitment of anti-inflammatory cells, increasing the M2 macrophage and FOXP3+ cell count in the infarcted area." (PMID 40725139, 2025). "CD4+ Foxp3+ CD25+ T-cells (Tregs) promote the healing process after myocardial infarction by engendering a pro-healing differentiation state in myocardial monocyte-derived macrophages." (PMID 38436707, 2024). "In terms of myocardial infarction, genetic ablation of Foxp3+ Tregs leads to pronounced infiltration by proinflammatory T cells and thus severe cardiac inflammation and impaired cardiac function." (PMID 32104149, 2020). "Collectively, the results shown here indicate that CD4+Foxp3+ Tregs act in a paracrine manner to promote CM proliferation during development, in both the maternal and the embryonic heart, and after myocardial infarction." (PMID 29946151, 2018). "We showed previously that stimulation of CD4+ Foxp3+ regulatory T-cells by superagonistic anti-CD28 monoclonal antibodies (mAb) improves myocardial healing after experimental myocardial infarction (MI)." (PMID 32298302, 2020). "CD4+CD25+Foxp3+ regulatory T cells (Treg cells) have protective effects in wound healing and adverse ventricular remodeling after myocardial infarction (MI)." (PMID 27144181, 2016). "Using unbiased transcriptomic profiling of cardiac T cell subsets after myocardial infarction, we identified reticulocalbin 3 (Rcn3) as one of the most selectively and robustly upregulated genes in neonatal CD4+Foxp3+ T (T-reg) cells." (PMID 41597278, 2026). "Myocardial infarction was induced in mice of different ages, and T cell subsets (CD4+ T cells, CD8+ T cells, and CD4+Foxp3+ T [T-reg] cells) were analyzed using flow cytometry and RNA sequencing." (PMID 41597278, 2026). "We chose four different time points after myocardial infarction and measured the levels of CD4+CD25+FOXP3 out of the total splenic CD4 population." (PMID 25436994, 2014).
myocarditis (13 papers, 2011 to 2024). Myocarditis is a condition that is characterized by inflammation of the heart muscle (myocardium). "Previous studies have linked activation of FoxP3+ T regulatory cells with resistance to CVB3 induced myocarditis, which is consistent with the current finding." (PMID 21806829, 2011). "For example, estrogen in women reduces levels of cardiac inflammation during myocarditis by activating a Th2‐type immune cells response, stimulation of Foxp3+ regulatory T cells, regulatory M2 macrophages, and inhibition of pro‐inflammatory T cells." (PMID 39570098, 2024). "Even more, Treg cells from myocarditis patients displayed higher levels of FOXP3 compared to controls." (PMID 35265721, 2022). "We decided to assess the levels of regulatory T cells, defined as CD4 + CD25 + FOXP3+ lymphocytes, from myocarditis patients and controls." (PMID 35265721, 2022). "We have previously shown that FoxP3- CD4+ T-lymphocytes significantly contribute to age-related myocardial inflammation in mice." (PMID 34046028, 2021). "Regulatory T cells, expressing forkhead box P3T (FOXP3), suppress effector cells and maintain immune homeostasis and tolerance in various autoimmune disease models, but their role in myocarditis is still debatable." (PMID 30035131, 2018). "Higher counts of Ki67+ and T-bet+ cells were found in cChHD as compared with GCM, whereas the expression of FOXP3 was very low in both myocarditis." (PMID 25144227, 2014). "This proinflammatory status, together with the impaired expression of FOXP3 in Tregs, may contribute to the pathogenesis and immune deregulation in acute myocarditis." (PMID 35265721, 2022). "However, when we analyzed the surface expression (MFI) of FOXP3 in these cells, we observed that myocarditis Treg lymphocytes expressed higher levels of FOXP3 (p = 0.04)." (PMID 35265721, 2022). "Therefore, we can deduce that FoxP3 may have an independent role in cardiac fibrosis and myocarditis." (PMID 35265221, 2022). "Adenovirus vector-mediated CTLA4Ig gene transfer in mice with EAM leads to downregulation of CTLA-4 and B7-2 proteins but upregulation of Treg, expression of FOXP3 and TGF-β mRNA, and alleviation of myocarditis." (PMID 30035131, 2018). "The current studies show that increased expression of c-FLIPS in T lymphocytes considerably increases CVB3-induced myocarditis and induction of autoimmune, heart-specific CD8+ effector T cells, while inhibiting CD4+ FoxP3+ T regulatory cell responses." (PMID 24816846, 2014). "Additionally, in a genetic mouse model of ICI‐related myocarditis, inflammatory cells observed in the heart comprised CD8+ T cells and a small number of CD4+ and FOXP3+ T cells." (PMID 38634742, 2024).
renal carcinoma (13 papers, 2010 to 2025). A carcinoma arising from the epithelium of the renal parenchyma or the renal pelvis. "After sunitinib treatment, the percentage of splenic FoxP3+ Tregs in mouse models of renal cancer and circulating Tregs in mRCC patients is decreased." (PMID 33854498, 2021). "In ovarian, colon, bladder, prostate, and renal cancers, FasL+ endothelial cells acquire the ability to kill T-cells while allowing FoxP3+ Tregs accumulation and infiltration." (PMID 33854498, 2021). "We detected Foxp3 protein in macrophages infiltrating mouse renal cancer tumors injected subcutaneously or in the kidney." (PMID 25264896, 2014). "Report on lung cell carcinomas prove that COX-2 derived PGE2 plays a significant role in the transformation of regulatory T cells, and researchers have found that COX-2 derived PGE2 in renal cancer can transform CD4+FOXP3− T cells into CD4+CD25+FOXP3+ regulatory T cells to escape the immune system." (PMID 33767709, 2021). "Immunohistochemistry showed the infiltrating distribution of Treg cell marker proteins FOXP3 and IL2RA in renal carcinoma tissue from the Human Protein Atlas database." (PMID 36846720, 2023). "Together, these findings confirmed the relationship of PTP4A3 to immune cell infiltration and CD79A, CSF1R, INOS, COX2, STAT5A, FOXP3 and CCR8 in KIRP, suggesting an important immune regulation role of PTP4A3 in the renal cancer microenvironment." (PMID 34630392, 2021).